PLIN1 (perilipin 1)
Diseases named in the same sentence as PLIN1 in open-access papers (continued):
Sharing a sentence is not in itself a finding about the gene and the disease.
glioma (3 papers, 2016 to 2025). A benign or malignant brain and spinal cord tumor that arises from glial cells (astrocytes, oligodendrocytes, ependymal cells). "Meanwhile, the level of PLIN1 is reduced in glioblastoma multiforme and patients with elevated PLIN1 levels are associated with better prognosis in low-grade glioma." (PMID 39870645, 2025). "Oil Red O staining assay revealed that PI3K inhibition increased lipid accumulation in glioma cells, while adding of si-PLIN1 reversed the effect of PI3K inhibitor." (PMID 39870645, 2025). "In conclusion, the dysregulation PI3K/AKT axis led to PLIN1 downregulation and the following tumor proliferation, invasion and lipid metabolism reprogramming in glioma." (PMID 39870645, 2025). "To investigate the mechanism of PLIN1 downregulation in glioma, we conducted both the KEGG and the GO analysis." (PMID 39870645, 2025). "To confirm PLIN1 level in glioma, we detected PLIN1 expression in 30 paired glioma samples and adjacent normal samples." (PMID 39870645, 2025). "Subsequent experiments revealed that up regulation of PLIN1 led to repressed cell growth and invasion in glioma." (PMID 39870645, 2025). "Taken together, this study claimed that PLIN1 acted as a tumor suppressor in glioma development and progression." (PMID 39870645, 2025). "On the other hand, we explored the effect of PLIN1 level on glioma outcome and found that low PLIN1 level was correlated with shortened OS of lower grade glioma." (PMID 39870645, 2025). "Here in this study, we conducted RNA next-generation sequencing with 33 glioma samples and 15 brain normal samples to discover that PLIN1 was downregulated in glioma." (PMID 39870645, 2025). "We concluded that the PI3K/AKT axis dysregulation led to PLIN1 downregulation and the following tumor growth and invasion of glioma." (PMID 39870645, 2025). "Here, we conducted RNA next-generation sequencing with 33 glioma samples and 15 brain normal samples to find that PLIN1 was downregulated in glioma." (PMID 39870645, 2025). "To better explore the impact of PLIN1 in glioma, we applied silencing vector to reduce the level of PLIN1 in SF126, T98 and SHG-44 cells." (PMID 39870645, 2025). "CCK-8 assay revealed that PI3K inhibition suppressed glioma cell proliferation, while adding of si-PLIN1 reversed the effect of PI3K inhibitor." (PMID 39870645, 2025). "This suggested that PLIN1 can be used as a biomarker to predict the sensitivity of glioma patients to temozolomide treatment." (PMID 37189627, 2023). "Here, we claimed that overexpression of PLIN1 repressed growth and invasion of glioma cells." (PMID 39870645, 2025). "CCK-8 assay revealed that up regulation of PLIN1 suppressed glioma proliferation." (PMID 39870645, 2025). "Next, we continued to explore the mechanism of PLIN1 downregulation in glioma." (PMID 39870645, 2025). "CCK-8 assay revealed that inhibition of PLIN1 enhanced glioma proliferation." (PMID 39870645, 2025). "Therefore, we focused on the potential regulation of PI3K signaling pathway in PLIN1 expression in glioma." (PMID 39870645, 2025). "But the possible biological function as well as mechanism of the PLIN1 in glioma is elusive so far." (PMID 39870645, 2025). "But the function and mechanism of PLIN1 in glioma lipid metabolism is still unclear nowadays." (PMID 39870645, 2025). "Further experiments revealed that PLIN1 up regulation led to repressed glioma growth and invasion." (PMID 39870645, 2025). "Besides, mice xenograft models were constructed to investigate the role of silencing PLIN1 in glioma in vivo." (PMID 39870645, 2025). "However, the role and molecular mechanism of PLIN1 in glioma lipid metabolism is uncertain nowadays." (PMID 39870645, 2025). "Besides, inhibition of PI3K suppressed glioma cell colony formation ability, which was also reversed by si-PLIN1." (PMID 39870645, 2025). "Thus, we applied overexpression vector to increase the level of PLIN1 in these three cells in order to explore the role of PLIN1 in glioma." (PMID 39870645, 2025).
glioma (continued). "Moreover, overexpression of PLIN1 increased lipid accumulation in glioma cells, with increasing expression of lipid biosynthesis related genes and decreasing expression of lipolysis related genes." (PMID 39870645, 2025). "Moreover, overexpression of PLIN1 increased the intracellular levels of TG in glioma cells, but decreased the levels of FFA." (PMID 39870645, 2025). "Mechanically, KEGG pathway analysis and GO analysis demonstrated the dysregulation of PI3K/AKT axis in glioma, which could lead to the downregulation of PLIN1 and the following tumor proliferation and invasion in glioma." (PMID 39870645, 2025). "We found Perilipin 1 (PLIN1) downregulated in glioma and correlated with poorer outcome." (PMID 39870645, 2025). "Thus, we concluded that PI3K/AKT axis dysregulation led to PLIN1 downregulation and the following tumor proliferation, invasion and lipid metabolism reprogramming in glioma." (PMID 39870645, 2025). "But the possible functions and mechanism of PLIN1 in glioma is still elusive." (PMID 39870645, 2025). "We further investigated whether there was a correlation between PLIN1/2/3/4/5 expression and the recurrence status of glioma." (PMID 37189627, 2023). "However, patients with PLIN1 amplification also exhibited low PLIN1 expression in low-grade glioma and pancreatic adenocarcinoma (p < 0.05)." (PMID 27359054, 2016). "Furthermore, the low PLIN1 mRNA levels also correlated with decreased overall survival in the other 3 human cancer types, including low-grade glioma, liver hepatocellular carcinoma and sarcoma." (PMID 27359054, 2016). "Moreover, Transwell assay showed that inhibition of PI3K suppressed glioma cell invasion and si-PLIN1 could reversed the effect of PI3K inhibitor." (PMID 39870645, 2025). "Moreover, low PLIN1 expression in glioma was correlated with worse outcome." (PMID 39870645, 2025). "Besides, PLIN1 overexpression suppressed glioma cell colony formation ability." (PMID 39870645, 2025). "Thus, we concluded that PI3K/AKT axis dysregulation led to PLIN1 downregulation in glioma." (PMID 39870645, 2025). "PLIN1 could act as a promising biomarker in glioma diagnosis, prognosis and treatment." (PMID 39870645, 2025). "Thus, we continued to find out the function of PLIN1 in glioma lipid metabolism." (PMID 39870645, 2025). "Besides, PLIN1 inhibition increased glioma cell colony formation ability." (PMID 39870645, 2025). "Moreover, inhibition of PLIN1 promoted glioma cell invasion." (PMID 39870645, 2025). "Here, we found that PI3K/AKT axis activity inhibition could increase PLIN1 levels in glioma." (PMID 39870645, 2025). "In addition, we determined that PLIN1 may affect glioma patients’ therapeutic sensitivity to temozolomide." (PMID 37189627, 2023). "Therefore, PLIN1 may enhance the malignant progression of gliomas and serve as a promising biomarker for predicting clinical prognosis and drug therapy." (PMID 37189627, 2023). "Moreover, we downloaded a lower grade glioma and glioblastoma (GBMLGG) dataset from TCGA and found out PLIN1 expressed lowly in primary tumor samples, and even lower in recurrent tumor tissues." (PMID 39870645, 2025). "Mechanically, we revealed that the PI3K/AKT axis could regulate PLIN1 levels in glioma, that inhibition of the activity of PI3K/AKT axis could increase PLIN1 levels in glioma." (PMID 39870645, 2025). "We also explored the correlation between PLINs and glioma-related targeted drugs and small molecule compounds through the GSCALiteOnline and Cellminer database, and we revealed that PLIN1 had a significant negative correlation with temozolomide, a drug commonly used in glioma." (PMID 37189627, 2023).
hepatocellular carcinoma (3 papers, 2016 to 2025). A malignant tumor that arises from hepatocytes. "The diagnosis and prognosis value of PLIN1 in hepatocellular carcinoma and the involved regulatory mechanism warrants in-depth study." (PMID 27359054, 2016). "In hepatocellular carcinoma (HCC), PLIN1 is also negatively expressed in HCC cell LDs." (PMID 39870645, 2025).
hypertrophic cardiomyopathy (3 papers, 2018 to 2022). A condition in which the myocardium is hypertrophied without an obvious cause. "PLIN1 deficiency in adipose tissue causes hypertension and hypertrophic cardiomyopathy." (PMID 36295596, 2022). "The lack of perilipin-1 in these mice resulted in enhanced fat tissue lipolysis associated with the development of hypertrophic cardiomyopathy and LV failure." (PMID 29320510, 2018).
lipoma (3 papers, 2020 to 2024). A benign, usually painless, well-circumscribed lipomatous tumor composed of adipose tissue. "All 24 well-differentiated liposarcomas were positive for PLIN1, 97.3% of 30 myxoid liposarcomas were positive for PLIN1, 72.7% of 13 pleomorphic liposarcomas were positive for PLIN1, and all 15 lipomas or angiolipomas were positive for PLIN1." (PMID 37998612, 2023). "Interestingly, the expression level of fat-specific gene PLIN1 was not changed between lipomas and WDLPS, consistently with the presence of comparable amount of fat in these two types of specimen." (PMID 32158531, 2020).
liposarcoma (3 papers, 2023 to 2025). A usually painless malignant tumor that arises from adipose tissue. "However, in 48 dedifferentiated liposarcomas, PLIN1 was positive only in the differentiated component." (PMID 37998612, 2023).
non-alcoholic fatty liver disease (3 papers, 2021 to 2023). "The lipid metabolism association of PLIN1 also has great potential for use in the diagnosis and treatment of nonalcoholic fatty liver disease." (PMID 37998612, 2023).
acquired generalized lipodystrophy (2 papers, 2023 to 2024). Acquired generalized lipodystrophy belongs to a group of lipodystrophic syndromes characterized by loss of adipose tissue, and is a syndrome of insulin resistance that leads to increased cardiovascular risk. "used PhIP-seq to detect autoantibodies to Perilipin-1 in a subset of patients with acquired generalized lipodystrophy." (PMID 39168282, 2024). "Anti-Plin1 antibodies were recently identified in patients with acquired generalized lipodystrophy, APS1, and cancer immunotherapy treatment." (PMID 37934865, 2023). "As noted, anti-PLIN1 is a known a marker for acquired generalized lipodystrophy in humans." (PMID 37934865, 2023).
acquired lipodystrophy (2 papers, 2024 to 2025). An instance of lipodystrophy (disease) that is acquired during the lifetime of the individual. "New insights into the immune response specificity in a subset of idiopathic acquired lipodystrophy cases further support the growing body of evidence suggesting PLIN1 autoantibodies as a potential biomarker for this syndrome." (PMID 40835790, 2025).
autoimmune disease (2 papers, 2024 to 2025). A disorder resulting from loss of function or tissue destruction of an organ or multiple organs, arising from humoral or cellular immune responses of the individual to their own tissue constituents. "Subsequently, two cohorts of patients with AGL were studied, and autoantibodies against PLIN1 were found in 37% and 50%, respectively, especially in patients with associated autoimmune diseases." (PMID 39785092, 2025). "AGL with anti‐PLIN1 antibodies has been reported to be associated with one or more autoimmune diseases in 82%–85% of cases, autoimmune hepatitis being the most frequent." (PMID 39785092, 2025). "Here, we report the clinical presentation and disease course of two pediatric patients with common autoimmune diseases (type 1 diabetes, autoimmune hepatitis) who developed AGL in the presence of anti‐PLIN1 antibodies." (PMID 39785092, 2025).
autoimmune hepatitis (2 papers, 2022 to 2025). Hepatitis caused by autoantibodies. "Perilipin 1- and 2-positive microvesicular steatotic foci were observed in 36% of HCV liver biopsies, and also in chronic hepatitis B, autoimmune hepatitis and mildly steatotic or normal livers, but less or none were observed in normal livers of younger patients." (PMID 36555099, 2022).
breast tumor (2 papers, 2016 to 2017). "Cells with PLIN1 over-expression produced much larger and faster growing breast tumors compared with control cells." (PMID 27359054, 2016). "To evaluate the effect of exogenous PLIN1 expression on the breast tumor growth in vivo, we established PLIN1-transfected stable or control MDA-MB-231 cells and injected them subcutaneously into nude mice." (PMID 27359054, 2016).
keloid (2 papers, 2022 to 2025). An irregularly shaped, elevated mark on the skin caused by deposits of excessive amounts of collagen during wound healing. "Immunofluorescence revealed the presence of RSL3 in these grafts, alongside a reduction in S100A4+FTH1+ fibroblast cells and PLIN1+α-SMA+ adipocyte cells in keloid grafts following RSL3 therapy, consistent with in vitro experiments." (PMID 40860189, 2025). "PPARGC1A, PPARG, PLIN1, LPL, ABHD5, lncRNA PART1, lncRNA ENTPD3-AS1 in trunk keloid and DGAT2 in ear keloid showed decreased trend under paired comparation." (PMID 35677827, 2022).
lung squamous cell carcinoma (2 papers, 2016 to 2023). "For the first time, we found that high PLIN1 expression was significantly correlated with worse disease-free survival (DFS) in lung squamous cell carcinoma (SCC)." (PMID 37998612, 2023). "Here, we focused on PLIN1, an important protein involved in lipid metabolism, and investigated the correlation between PLIN1 expression and the prognosis of lung squamous cell carcinoma." (PMID 37998612, 2023).
non-alcoholic steatohepatitis (2 papers, 2014 to 2023). "In the liver, Perilipin 2 (Plin2) is the most abundant lipid droplet protein; while Perilipin 3 (Plin3) is mildly expressed and Perilipin 1 (Plin1) is de novo expressed in non-alcoholic steatohepatitis." (PMID 24831094, 2014). "In our recent study, Plin1 is barely detectable and to our knowledge, de novo expression of hepatic Plin1 has only been reported in non-alcoholic steatohepatitis." (PMID 24831094, 2014). "NAFLD (non-alcoholic steatohepatitis, NASH) leads to an upregulation of PLIN1." (PMID 36950134, 2023).
Alzheimer disease (1 paper, 2021). A progressive, neurodegenerative disease characterized by loss of function and death of nerve cells in several areas of the brain leading to loss of cognitive function such as memory and language. "Finally, a recent expression study on all human perlipin proteins (PLIN1-5), found that PLIN2 accumulates, particularly in neurons, in brains of old subjects and of patients with Alzheimer disease." (PMID 34788284, 2021).
brain glioma (1 paper, 2016). A malignant glioma that involves the brain. "Furthermore, we found that low expression of PLIN1 in human brain glioma significantly correlates with the WHO classification (p < 0.01), which signifies that decreased PLIN1 occurs more frequently in advanced tumors." (PMID 27359054, 2016).
dermatofibrosarcoma protuberans (1 paper, 2020). Dermatofibrosarcoma protuberans (DFSP) is a rare infiltrating soft tissue sarcoma, generally of low grade malignancy, arising from the dermis of the skin and characteristically associated with a specific chromosomal translocation t(17;22). "PLIN1 was absent from non-lipomatous sarcomas (0/179), PLIN2 expressed in all fibrosarcomas (18/18), Ewing's sarcomas (17/17), epithelioid sarcomas (8/8), and in most rhabdomyosarcomas (17/22), leiomyosarcomas (31/42), dermatofibrosarcoma protuberans (23/38), and undifferentiated sarcomas (33/34)." (PMID 32368290, 2020).
Fanconi anemia (1 paper, 2025). Fanconi anemia (FA) is a hereditary DNA repair disorder characterized by progressive pancytopenia with bone marrow failure, variable congenital malformations and predisposition to develop hematological or solid tumors. "The pathways with significantly enriched DEGs in PLIN1-overexpressed hGCs and phGCs include the TGF-beta signaling pathway, the Fanconi anemia pathway, and the adherens junction." (PMID 39858284, 2025).
Fibroadenoma (1 paper, 2020). A benign tumor of the breast characterized by the presence of stromal and epithelial elements. "Furthermore, the expression of seven step-changing proteins (KRT10, KRT1, KRT6E, PLIN1, HBA2, FHL1, and ME2) were decreased in fibroadenoma tissues compared to fibroadenoma adjacent and normal tissues." (PMID 33194682, 2020).
gastric cancer (1 paper, 2022). A primary or metastatic malignant neoplasm involving the stomach. "We transfected with gastric cancer cell lines with miR-193a-3p and transfected supernatant was collected to co-culture with 3T3-L1, the adipogenesis specific genes C/EBPα, PPARγ and Perilipin-1 were evidently elevated, and DLK1 was down-regulated in mimic group." (PMID 35541892, 2022).
heart failure (1 paper, 2018). Inability of the heart to pump blood at an adequate rate to meet tissue metabolic requirements. "The relevance of adipose tissue lipolysis in heart failure development has recently been supported by a study in mice deficient for the adipose-specific perilipin-1 isoform." (PMID 29320510, 2018).
ischemia (1 paper, 2023). A hypoperfusion of the BLOOD through an organ or tissue caused by a PATHOLOGIC CONSTRICTION or obstruction of its BLOOD VESSELS, or an absence of BLOOD CIRCULATION. "We checked for ischemia‐induced DEGs encoding typical lipid droplet membrane protein components, such as PLIN1‐5 family, and the reported IFN‐induced lipid droplet‐associated proteins." (PMID 36541061, 2023).
lactic acidosis (1 paper, 2023). Metabolic acidosis characterized by the accumulation of lactate in the body. "Briefly, we observed a significant decrease in FABP4, adiponectin, and perilipin-1 protein expression both in acADSCs grown under lactic acidosis and in those treated with TGFβ1 compared to basal conditions." (PMID 36980280, 2023). "In particular, the percentages of perilipin-1-positive and adiponectin-positive cells/hpf were approximately three times decreased in acADSCs grown under lactic acidosis, as well as following TGFβ1 treatment, compared to those maintained in basal (pH 7.4) medium." (PMID 36980280, 2023). "Briefly, we demonstrated that acADSCs grown under lactic acidosis conditions lose the adipocyte differentiation markers FABP4, C/EBPα, adiponectin, and perilipin-1 while acquiring the myofibroblast markers α-SMA, COL1A1, and COL1A2." (PMID 36980280, 2023).
lipid metabolic disorders (1 paper, 2018). "Therefore, PLIN1 may be a valuable target to prevent lipid metabolic disorders and the overproduction of inflammatory cytokines in the adipocytes of cows with ketosis." (PMID 29593725, 2018).
liver disease (1 paper, 2016). "Here, accumulation of ADFP, but not PLIN1, suggests a specific role of ADFP in HBx-induced liver disease." (PMID 27708241, 2016).
liver fibrosis (1 paper, 2020). "FXR agonists elicit their clinical benefits to retarding liver fibrosis mainly via upregulating Plin1 and thereby stabilizing LDs for preventing HSCs activation." (PMID 31932588, 2020).
lung carcinoma (1 paper, 2023). "To date, no studies have addressed the association between the prognosis of lung cancer and PLIN1 expression." (PMID 37998612, 2023). "To date, no studies have reported on the prognosis of lung cancer and PLIN1 expression." (PMID 37998612, 2023).
lymph node metastasis (1 paper, 2023). "The correlation between lymph node metastasis and PLIN1 expression was also not significant with a p value of 0.273, and the association between distant metastasis and PLIN1 expression was not statistically significant with a p value of 0.714." (PMID 37998612, 2023).